CXCL1 (C-X-C motif chemokine ligand 1)
Diseases named in the same sentence as CXCL1 in open-access papers (continued):
Sharing a sentence is not in itself a finding about the gene and the disease.
tumor (continued). "The considerable CXCL1-dependent inhibition of the expression of CCL2 and CCL28, also endowed with an immunostimulating, but also pro-tumoral effect, emphasizes the critical role of the final equilibrium among the multiple microenvironmental signals in driving BCSC fate and tumor behavior." (PMID 34195201, 2021). "On the other hand, CXCL1 and CXCL2, that are produced upon appropriate stimulation by a variety of cell types including monocytes/macrophages, neutrophils, epithelial cells and also tumor cells, have functions beyond attracting neutrophil granulocytes to the site of infection or damage." (PMID 32276475, 2020). "On the other hand, the CXCL1 and IL–8 gradient produced by AgNPs treated MDA-MB-436 cells may attract myeloid-derived suppressor cells (MDSCs) that preferentially infiltrate the primary tumor site than metastases." (PMID 32443890, 2020). "In addition, suppressing the action of proangiogenic cytokines induced by HEYL using a small molecule inhibitor of the CXCl1/2/3 receptor, CXCR2, in combination with the anti-VEGF monoclonal antibody, bevacizumab, significantly reduced tumor growth of MDA-MB-231 xenografts." (PMID 33520697, 2020). "Interestingly, the interaction of MSC with tumor cells modifies their trophic properties through the release of various cytokines such as CXCL1, CXCL2, CXCL12 or IL-6 and metalloproteinases (MMPs) that can degrade the extracellular matrix and promote tumor migration." (PMID 33081024, 2020). "Interestingly, however, chronic circulating markers of inflammation (i.e., IL-6, CXCL1) were observed in mouse models even after tumor resection, suggesting long-term changes due to the cancer or surgery even when the tumor is no longer present." (PMID 33302472, 2020). "However, the Cxcl1 level, another pro-inflammatory chemokine, was drastically increased (~30–60-fold) in the same LLC-derived tumor samples, which is the opposite to the suppressed features (~7–8-fold) shown in TRAMP-C1 derived tumor tissues." (PMID 32244522, 2020). "Therefore, IL-33 may induce chemokines (e.g. Cxcl1), which enhanced the recruitment of myeloid cells secreting S100A9 to promote tumour progression." (PMID 33308251, 2020). "The transcription of Tnfα, Cxcl1, Ccl2, and Ccl20 was upregulated in Spont-PyMT tumors, like in Trans-PyMT ones, even though the fold increases were not always similar in the two tumor types." (PMID 31511510, 2019). "Specifically, a smaller tumor size was correlated with increases in CD45+CD11b+ cells present in the tumors (r = −0.956; p = 0.04), in serum MPO (r = −0.969; p = 0.03), in serum IL-5 (r = −0.948; p = 0.051), and in serum CXCL1 (r = −0.938; p = 0.06) concentrations." (PMID 31114758, 2019). "Also unlike hematological malignancies that are easy to be targeted and reached by CAR-T cells, some of chemokines such as CXCL1 23, CXCL12, and CXCL5 24, 25 secreted by solid tumors prevent T cells from trafficking toward and infiltrating into the tumor lesions." (PMID 31754328, 2019). "Unlike known MDSCs, MLACs lack the ability to suppress cytotoxic T lymphocytes and differentiate into tumor-associated macrophages (TAMs), but could still directly facilitate tumor growth and angiogenesis through secreting CCL2, CXCL1/2/5, PAI-1, MMPs, and VEGFA." (PMID 29541408, 2018). "Tumor upregulated chemokines included the followings: CXCL5 (138 fold increase); CCL25 (70 fold increase); CXCL11 (26 fold increase); CXCL6 (20 fold increase); CXCL1 and CXCL10 (11 fold increase); CXCL3 (8 fold increase); and CXCL9, CXCL2, and CCL3L1 (6 fold increase)." (PMID 29088818, 2017). "Furthermore, the IL-8/CXCR1/CXCR2 signaling was crucial for the maintenance of stemness features and tumor-initiating ability of TC cells, whereas CXCL1/CXCR2 was not." (PMID 28415590, 2017).
tumor (continued). "Upon blockage of CAF-secreted CXCL1 signaling by 500 ng/ml CXCL1 antibody or by 400 nM CXCR2 inhibitor SB225002, CAF-enhanced ROS increase following radiation was attenuated in KYSE-30 and in KYSE-150, suggesting CAF-secreted CXCL1 enhanced ROS increase following radiation in tumor cells." (PMID 28518141, 2017). "Interestingly, the previously reported tumor angiogenesis gene HMGB1 displays parallel actions to BRD7 knockdown as it induces the expression of different pro-angiogenic cytokines, including IL8, CXCL1 and CXCL6." (PMID 28951988, 2017). "Collectively, our data indicates that, in addition to controlling tumor-specific proliferation, the IL-17RC-A20 axis has a regulatory role in selectively repressing production of pro-inflammatory cytokines, including IL-6 and GM-CSF, but not CXCL1." (PMID 28562353, 2017). "Together suggest that IL-1β secreted from IRISOE tumor cells upregulates expression of its own receptor; IL-1R on the surface of naïve MSCs only, leading to activation of AKT, ERK, and p65/NF-κB signaling within MSCs, which leads to secretion of CXCL1 from MSCs." (PMID 29262555, 2017). "However, there is little evidence directly elucidating the function of tumor-derived CXCL1 on the migration of neutrophils/granulocytic cells." (PMID 27446967, 2016). "However, the expression levels of Fas/FasL in TANs did not depend on the CXCL1 expression in primary tumor cells." (PMID 27446967, 2016). "IHC staining of Ki-67 and proliferating cell nuclear antigen (PCNA) was performed on the tumors and, in comparison to the negative control, upregulation of CXCL1 significantly promoted proliferation, as indicated by the number of tumor cells positive for Ki-67 and PCNA staining." (PMID 27542259, 2016). "When neutrophils were recruited to peritoneal cavity with CXCL1-expressing cells (C-PC, non-inflammatory), the neutrophils from tumor-bearing mice and pG/pI6-mice showed a protumor phenotype, characterized by higher expression of Bv8 and Mmp9 as well as lower expression of Rab27a and Trail." (PMID 25587026, 2014). "Thus, we inferred that the HPSE miRNA could block the expression of IL8 and CXCL1, thus impairing the effect of IL8 and CXCL1 on the migration and invasion of tumor cells." (PMID 22719918, 2012). "However the ability of CCL2, CXCL1, CXCL5 and VEGF to significantly reduce IL-12p70 production by DCs is important, as this may potentially result in a reduced anti-tumour Th1 response in vivo." (PMID 22125641, 2011). "Furthermore, we detected a significant clinicopathological association between CXCL5 expression and early tumor categories of CRC (P < 0.001), which did not occur for CXCL1 or CXCL6." (PMID 18578857, 2008). "In addition, the expression of several pro-inflammatory cytokines and chemokines such as IL-1β, IL-22, TNF-α, CXCL1, CXCL2, CCL17 and CCL20 were reduced in IL-38KO mice, suggesting that IL-38 promotes tumour growth and development in cSSC through promoting an inflammatory tumour environment." (PMID 40057603, 2025). "Additionally, in a mouse model, VEGF‐A secreted by colorectal cancer cells stimulated the production of CXCL1 by TAM and recruited CXCR2+ MDSCs from the circulatory system into the premetastatic liver, further serving as support cells to maintain the survival of tumor cells with liver metastasis." (PMID 40452814, 2025). "Urinary CXCL1 levels may or may not correlate with tumor stage depending on the study cited." (PMID 38673949, 2024). "However, the roles of tumor cell-secreted CXCL1 in the progression of OSCC are not fully clear." (PMID 38713320, 2024). "Indeed, the tumor cores (L and LB) were found to express numerous pEMT genes at significantly greater levels than the TME, including the laminins (LAMC1, LAMC2, LAMA3), integrins (ITGA2, ITGB1, ITGAV), and inflammatory and neutrophil-attracting chemokines (CXCL8, CXCL1)." (PMID 36216799, 2022).
tumor (continued). "In addition, CXCL1/5 promotes neutrophil recruitment and IL-17A produced by neutrophils stimulates EOC stromal cells to secrete CXCL1, thereby attracting more neutrophils to form an aberrant immune environment that promotes cancer progression and suppresses anti-tumor immune responses." (PMID 35269786, 2022). "However, as the role of CXCL1 in immune cell intravasation of lymphatic vessels is not clear, this case may not reflect immune cell mimicry by tumor cells." (PMID 34685565, 2021). "Our findings suggested that SETD2 inhibited tumor growth via suppressing CXCL1-mediated activation of cell cycle, indicating that the regulation of H3K36me3 level by targeting SETD2 and/or the administration of downstream CXCL1 might represent a potential therapeutic way for new treatment in LUAD." (PMID 33223508, 2020). "While the effect of CXCL1 and CXCL5 on DC maturation and cytokine secretion has not been previously investigated, their known function is to attract and activate neutrophils, which in turn have been implicated with tumour cell growth, angiogenesis and metastasis." (PMID 22125641, 2011). "Consistent with the transcriptomic findings, immunohistochemistry confirmed higher expression of NOX4, CXCL1, CDKN2A, and SIX1 in CRC tissues than in paired adjacent non-tumor tissues." (PMID 42317343, 2026). "MSI analysis revealed significant positive correlations for TACC3 and CXCL1 (p < 0.05), suggesting their potential roles in MSI-high tumor biology, whereas ABCB1, TGFBI, and VDR lacked significant associations with MSI status." (PMID 40791849, 2025). "qPCR analysis of the tumor tissue indicated that the presence of CAF during tumorigenesis upregulated the expression of CXCL5, whereas the expression of CXCL1, 2, 3, 6, 7, 8, and IL-6 were not significantly affected." (PMID 41392310, 2025). "Elevated levels of CXCL1 were observed in TKTB34-RAS and TKTB6-RAS tumor-bearing mice compared with control groups without tumors." (PMID 38651826, 2024). "For example, CAFs found in luminal non-specified and stroma-rich subtypes can secrete CXCL1, CXCL2, CXCL12, and CXCL14, contributing to tumor progression." (PMID 39409924, 2024). "As a control, we knocked out CXCL1 in HCT116 cells, which did not impact the xenograft tumor growth." (PMID 38194275, 2024). "Consistently, the production and expression of the chemokines CXCL1 and CXCL2, but not CCL3 and CCL5, were significantly upregulated in serum and tumor-infiltrating neutrophils from Arnt−/− mice." (PMID 36859266, 2023). "Similar to CXCL1, CXCL8 expression was demonstrated in BC tumor samples where mRNA levels were independent of tumor size and stage, metastatic abundance, and chemotherapy efficacy." (PMID 36431173, 2022). "Collectively, neutrophils migrated to PTT-treated tumors along chemokine gradients of CXCL1 and MIP-2, irrespective of the type of tumors and PTT transducers, as well as the tumor size." (PMID 32111847, 2020). "This increase in migration was dependent on the concentration of CXCL1, but not CXCL8 in the tumor supernatants." (PMID 28923105, 2017). "Consistent with the tumour growth data, in obese, but not in lean, mice there was a sevenfold higher frequency of CXCR1+ ASCs observed in CXCL1-sh-RM1 tumours, compared with control-sh-RM1 tumours." (PMID 27241286, 2016). "It is surprising that inhibition of CXCL1, which is also a CXCR2 agonist similar to CXCL2, exerted no inhibitory effects on the tumor suppression and neutrophil infiltration induced by HVJ-E+poly I:C treatment." (PMID 27259252, 2016). "CXCL1 expression observed in control-sh-RM1 tumours was expectedly absent in CXCL1-sh-RM1 tumours, indicating cancer cells as the main source of tumour-secreted CXCL1." (PMID 27241286, 2016). "In comparison to those of the non-target shRNA control, the mean tumor volumes of SW620 cells were decreased by 71% and 73% in the presence of two distinct CXCL1 shRNAs." (PMID 26104296, 2015).
tumor (continued). "As in the tumor tissue, TGFβ upregulated IL-6 and, VEGF, and downregulated MCP1, CXCL1, and CXCL5 in cells with and without DNIIR expression." (PMID 25280532, 2014). "On the other hand, CXCL1, but not anti-CXCL8, was found to be responsible of mediating tumor-derived angiogenesis in human DU145 prostate cancer cell line." (PMID 24971349, 2014). "We found that expression of CXCL1, but not CXCL5, decreased significantly in patients with low TGFBR2 expression, but when we analyzed subtypes of tumor we discovered significant differences only in HER2+, PR + and ER + patients." (PMID 25280532, 2014). "Addition of antibodies against CXCL1, CD81, and TPT1 had various effects either inhibiting the tumor proliferation or showing no significant changes upon the tumors." (PMID 19558675, 2009). "The fact that addition of an antibody enhances the suppressive effect of HiB5 and ST14A on tumor growth gives hints that the suppressive effect of these NPC is not due to their secretion of TPT1, CD81 and CXCL1, Gas6/Axl but to other factors." (PMID 19558675, 2009). "Further experiments were conducted on hBMECs to determine the effects of DEX, docetaxel and a combination of DEX with docetaxel on IL-8 and CXCL1 gene transcription and the secretion of these CXC-chemokines by endothelial rather than tumour cells." (PMID 19050703, 2008). "Unlike S100A8/A9, the abundance of CXCL1, CXCL2, and CXCL5 chemokines in scaffolds neither increased following the infiltration of cancer-induced neutrophils in MNs after tumor inoculation nor decreased after systemic depletion of neutrophils in tumor-bearing mice." (PMID 37553342, 2023). "ADU-S100 administered as monotherapy had a significant effect on release of CXCL1, IFN-β, IFN-γ, and TNF-α, but only intratumorally not systemically, which could explain the slightly reduced abscopal anti-tumor effects seen in mice treated with ADU-S100 alone." (PMID 37465665, 2023). "CXCL1 does not act on HCC cancer stem cells, only on other cells in the tumor niche." (PMID 37408240, 2023). "The absence of CD14-positive cells within the tumour epithelium in ACP is unexpected as the β-catenin-accumulating epithelial whorls (cell clusters) express a variety of chemo-attractant cytokines (e.g., members of the CCL and CXCL family of chemokines including CCL2, CXCL1, CXCL3, CXCL11)." (PMID 39127699, 2024). "Importantly, CXCL1 concentration in tumor lysates was found to be significantly higher than in plasma from corresponding mice, whereas the level of CXCL5 did not significantly differ in tumor and plasma samples." (PMID 33578808, 2021). "So far, we have identified CXCL1, IL10 and CCL4 in exercise-conditioned serum of advanced PC patients; it will be important to know if these myokines are generally induced by exercise, independent of the tumour type and its characteristics (e.g., aggressiveness or hormone dependency)." (PMID 34359731, 2021). "To further detect whether the alterations in the chemokine profiles were critical in USP12-mediated control of tumour growth, we overexpressed Cxcl1 combined with or without Ccl2 into mouse lung tumour cells and found that LLC cells, when overexpressing Cxcl1, grew more rapidly than control cells." (PMID 34381028, 2021). "Unexpected results enhancing mRNA levels of CCL20 rather than CXCL1/2 in CXCR2-driven ovarian progression indicate the diversity and complex of chemokine network between cell culture system with homogenous interaction and tumor progression via heterogeneous interaction with other cell types." (PMID 27723802, 2016).
infection (642 papers, 2007 to 2026). The state of being infected such as from the introduction of a foreign agent such as serum, vaccine, antigenic substance or organism. "Neutralizing CXCL1 significantly alleviated the neuropathological changes caused by EV-A71 infection, and the production of CXCL1 in astrocytes was regulated by p38 MAPK signaling." (PMID 39679722, 2025). "Following EV-A71 infection, we further investigated the glial populations associated with CXCL1 production by preparing whole-brain tissues for confocal microscopy." (PMID 39679722, 2025). "In astrocytes, infection with HSV-1 induces this cell population to secrete CXCL1, which causes the increased migration of neutrophils to the site of infection." (PMID 38248274, 2024). "The chemokine CXCL-1 is associated with neutrophil recruitment and is important in combating early infection, although prolonged neutrophil accumulation is associated with deleterious inflammation." (PMID 37424774, 2023). "Infection with A. actinomycetemcomitans caused a significant upregulation in the expression levels of Isg15, Mx1, Mx2, Irf3, Irf7, Tlr-2, Tnf-α, Cxcl-1, and Il-6 genes." (PMID 37929187, 2023). "At day 3 post-infection, young and aged neutrophils expressed similar levels of Il1b, but young neutrophils expressed higher levels of Il1a; the chemokines Ccl3, Cxcl3, and Cxcl1; and Cd274 (encodes PD-L1)." (PMID 37852965, 2023). "Infection with A. actinomycetemcomitans as a single species caused a significant increase in IL-2, CXCL1, CCL-3/MIP1α, and G-CSF levels compared to sterile implants." (PMID 35203495, 2022). "We observed that increased susceptibility to infection was accompanied by increased neutrophil recruitment and IL-1, CXCL1, and CXCL5 levels in the lung homogenates." (PMID 36119114, 2022). "As detailed above, using a model of challenge with killed GAS or S. aureus, IL-1-deficient mice showed a severe defect in CXCL1/2 production and impaired recruitment of neutrophils to peripheral sites of infection." (PMID 33525468, 2021). "Treatment with proteasome inhibitor significantly inhibited the release of IL-1, IL-6, TNFα, MIP-1β (i.e. CCL4), and KC (i.e. CXCL1) at their peak time-points in Balb/c mice after infection with the highly pathogenic avian H5N1 influenza A virus." (PMID 33362782, 2020). "Whilst an increase in CXCL1(KC) was observed in the lungs upon re-infection in RAGE deficient mice, this response was significantly lower than that of WT mice." (PMID 28099113, 2017). "In contrast to IFN-β expression, actin polymerization was only partially implicated in DC expression of IL-6 and CXCL1 following infection with the S. suis strain P1/7." (PMID 28894449, 2017). "Pulmonary levels of IFNγ, IL-1α, IL-1β and CXCL1/KC were highly increased in TNFα-deficient mice one month after infection, when severe pathology develops, with a reduction of IL-12/23p40 and p19, in line with transcriptome data." (PMID 27853279, 2016). "In a GBS-infection model, IL-1β deficiency has been associated with selective impairment in the production of the neutrophil chemokine CXCL1." (PMID 27527222, 2016). "The more severe infection in IL-17A−/− mice was associated with a significant reduction in CXCL1 (KC) production and impaired neutrophil recruitment to the lungs post challenge." (PMID 23592988, 2013). "Bacterial dissemination was associated with significant reductions of CXCL1 (KC), polymorphonuclear cells (PMNs), and extracellular DNA traps (NETs) at the infection site." (PMID 22844481, 2012). "Moreover, previous studies have indicated that the increased susceptibility to infection observed in Cxcr2-/- and Cxcl1-/- mice is linked to impaired neutrophil recruitment into infected tissues." (PMID 41451234, 2025).